IL10 (interleukin 10)
Diseases named in the same sentence as IL10 in open-access papers (continued):
Sharing a sentence is not in itself a finding about the gene and the disease.
schizophrenia (continued). "The reduced production of IL-10 following ErbB stimulation in schizophrenia suggests an enhanced inflammatory phenotype and a dysfunctional anti-inflammatory effect of NRG162." (PMID 28646138, 2017). "In the case of TLR4 stimulation, there were significantly weaker IL-1β, IL-6, and TNF-α responses in schizophrenia relative to the control subjects (p < 0.01), whereas IL-10 production was intact (p > 0.5)." (PMID 28646138, 2017). "From these results, it is highly probable that anti-inflammatory responses mediated by IL-10 and IL-13, which reflect M2 polarization of microglia, occur in the CNS of schizophrenia patients." (PMID 25429645, 2014). "Recently, relatively higher amounts of IL-10 and IL-13 have been found in the CSF and blood from patients with schizophrenia." (PMID 25429645, 2014). "An immune response shifting from Type 1 (including one cytokine interleukin-2(IL2)) to Type 2 (including one cytokine interleukin-10(IL10)) happens in schizophrenia." (PMID 23951054, 2013). "Both IL-10 SNPs and haplotypes have been reported to be in linkage disequilibrium with schizophrenia in some populations." (PMID 21658228, 2011). "There is evidence of the role of IL-10 in the neurodevelopmental abnormalities found in schizophrenia." (PMID 21658228, 2011). "Specifically the recent report by Sun highlights the IL-10 signaling as a candidate pathway in schizophrenia." (PMID 21658228, 2011). "IL-10 and COMT gene polymorphisms were found to interact with cognitive function in patients with schizophrenia, suggesting that COMT may influence immune responses through interaction with anti-inflammatory cytokines." (PMID 40299330, 2025). "Additionally, increased concentrations of IL-1β, IL-6, IL-10, IL-17, and sIL-2, and a reduction in TNF-α are associated with more severe positive symptoms of schizophrenia." (PMID 40364201, 2025). "The finding of elevated IL-10 in our sample is partially at odds with some studies that have reported predominantly pro-inflammatory profiles in patients with first-episode schizophrenia, as well as research identifying reduced IL-10 levels in patients during acute relapses." (PMID 41008291, 2025). "has shown that IL-10 serum levels are markedly lower in drug-naïve people with schizophrenia." (PMID 37868103, 2024). "Therefore, this study attempts to establish associations between serum cytokines IL-6, IL-12, IL-5, IL-10 and TGF-β1 changes and the effectiveness of ECT in treatment-resistant schizophrenia patients." (PMID 39595201, 2024). "Although serum IL-10 levels are elevated, immunosuppressive effects might compensate for prior elevations in pro-inflammatory cytokines in people with schizophrenia." (PMID 37868103, 2024). "Importantly, the IL-10/IL-6 ratio was lower in the SZ group, which indicates the predominance of pro-inflammatory processes in schizophrenia." (PMID 37239308, 2023). "However, it should be noted that a number of studies have found an increase in the concentration of IL-10 in patients with schizophrenia." (PMID 37239308, 2023). "Previously, we have established for the first time that the immunological profile, which is characterized by the increase of IL-10 content and moderate signs of systemic inflammation, is associated with marked negative symptoms in patients with schizophrenia." (PMID 39944368, 2023). "Moreover, several studies found an increase in cytokines levels, including IL-6 and IL-10 in suicidal victims (Schizophrenia Working Group of the Psychiatric Genomics Consortium, 2014)." (PMID 37183855, 2023). "Human postmortem studies carried out on individuals diagnosed with schizophrenia, brain samples showed lower tlr4 mRNA and protein levels, and downregulation of il6, il10, and tnfa mRNA in the prefrontal cortex (PFC) region, and elevated TLR4 protein levels in the cerebellum region." (PMID 37627253, 2023).
schizophrenia (continued). "The link between the upregulation of proinflammatory cytokine IL-10 and ≥10-year duration of schizophrenia may be explained by the activation of compensatory mechanisms." (PMID 36556337, 2022). "IL-1β, IL-22, G-CSF, IL-21, and IL-10 were significantly higher in schizophrenia than in controls." (PMID 36256663, 2022). "Likewise, IL-12, IL-6, TNF and IFNγ peripherical levels are enhanced in patients with schizophrenia, and IL-6 and IL-10 levels elevated in children with ADHD." (PMID 34610039, 2021). "Additionally, the study confirmed more significant interactive effects of genotypes of COMT and IL-10 on cognition in schizophrenia patients than in controls." (PMID 34725583, 2021). "Schizophrenia has also been shown to be associated with polymorphisms of numerous genes responsible for the synthesis of such cytokines as IL1A, IL1B, IL10 and IL6, which are genes for, respectively, IL-1α, IL-1β, IL-10 and IL-6." (PMID 34501305, 2021). "Interestingly, our results indicated that IL-6 and IL-10 levels were both correlated with BMI in schizophrenia patients (r = 0.233, P = 0.010; r = 0.204, P = 0.025, respectively)." (PMID 33324265, 2020). "After confirming that rIL-10 mirror the possible mechanism of MSC in vitro, we wondered whether intravenous IL-10 infusion also inhibited schizophrenia-relevant behaviors in amphetamine-sensitized mice." (PMID 32341334, 2020). "A question arises as to whether a single injection of hUC-MSC can achieve sustained elevation of IL-10 and inhibit induction of schizophrenia-relevant behaviors in amphetamine-sensitized mice." (PMID 32341334, 2020). "Focusing on IL-10, a key anti-inflammatory cytokine, the current study provided direct evidence supporting that elevated peripheral IL-10 was related to the disrupted WM integrity of certain bundles in schizophrenia." (PMID 30792621, 2019). "Given that increased RD is related to demyelination, the pattern that higher IL-10 is related to higher RD in schizophrenia, as observed in our study, further supports that IL-10 may be involved in the demyelination of WM." (PMID 30792621, 2019). "In addition, a meta-analysis of genomic studies demonstrated that subjects with a single nucleotide polymorphism (SNP, rs1800872) and two haplotypes (A-C-A and G-C-C) of IL-10 are vulnerable to schizophrenia." (PMID 30792621, 2019). "Peripheral IL-10 levels were also correlated to the severity of clinical symptoms of schizophrenia." (PMID 30792621, 2019). "In our study, systemic IL-10 levels were higher in schizophrenia patients than in healthy subjects, consistent with previous studies and further supporting that the dysregulation of systemic IL-10 is related to the pathogenesis of schizophrenia." (PMID 30792621, 2019). "Furthermore, a previous study found an elevation of systemic IL-10 in patients with schizophrenia compared with healthy controls." (PMID 30792621, 2019). "Notably, IL-4 and IL-10 elevations were highly significant in this meta-analysis, but are less frequently identified in patients with schizophrenia." (PMID 29803226, 2018). "Single nucleotide polymorphisms have been analysed in many cytokines, in particular, those that are associated with altered levels in schizophrenia such as TNF-α, IL1-β, IL-6, IL-10, INF-γ, and in the genes encoding the immune system regulatory proteins CTLA-4 and CD28." (PMID 29317797, 2017). "The magnitude of increase in IL-1β, IL-6, IL-8 and IL-10 mRNAs in people in the elevated inflammation biotype ranged from 100 to 220% of those in the non-elevated inflammatory biotype and was comparable between control and schizophrenia groups." (PMID 28923068, 2017). "A significant increase in IL-10 levels has been reported in the serum of schizophrenia patients." (PMID 25429645, 2014). "In addition, Interleukin (IL)-6 serum levels were significantly increased in patients with schizophrenia as compared with controls, whereas IL-10 concentration was increased in both patients with schizophrenia and BPD." (PMID 22505994, 2012).
schizophrenia (continued). "In addition, the different diagnostic subtypes of schizophrenia, paranoid or non-paranoid, also be found for an immunologically difference in IL-10 response, which indicating a possibility that IL-10 involved in the pathogenesis of schizophrenia." (PMID 23675088, 2008). "It seems that IL-10 might correlate to schizophrenia base on the hypotheses of Th2-like immunity shift of susceptible allele carrier." (PMID 23675088, 2008). "This study suggests that elevated peripheral levels of TGF-β, but not IL-6, IL-1β, TNF-α, IFN-γ or IL-10, may not only predispose one to the development of schizophrenia, but may also be a consequence of childhood trauma." (PMID 34501305, 2021). "Although the mechanism of reduced FA in schizophrenia is not well-known yet, it is important to note that high IL-10 levels in serum were negatively associated with reduced FA in the posterior thalamic radiata and the inferior fronto-occipital fasciculus in our study." (PMID 30792621, 2019). "Thus, the aim of the present study was to explore whether the changes of peripheral IL-10 were related to the disruption of microstructural WM integrity in vivo and clinical symptoms, as well as cognitive ratings in schizophrenia." (PMID 30792621, 2019). "Patients with first episode of schizophrenia as well as its relapse were reported to have increased serum level of IL-6, tumor necrosis factor α, IL-1β, and interferon-γ and decreased serum concentration of anti-inflammatory interleukin-10 (IL-10) (Müller 2018)." (PMID 30178287, 2019). "The evidence suggests that WM injury may occur under high serum IL-10 in schizophrenia." (PMID 30792621, 2019). "In clinical trials, abnormal production of IL-6 and TNF-α in the peripheral blood of patients with schizophrenia and other psychotic disorders is the most replicated finding, whereas the participation of anti-inflammatory cytokines, such as IL-10, remains poorly explored." (PMID 30686977, 2018). "The finding that only IL-10 responded to treatment in parallel with symptom improvement suggests that it could be used as a potential treatment response biomarker in future studies of schizophrenia." (PMID 28870209, 2017). "Similarly, IL-10 from M2 microglia may contribute to remission in schizophrenia by inhibiting pro-inflammatory cytokine production in M1 microglia." (PMID 25429645, 2014). "Furthermore, in a recent meta-analysis in which the effect of 10 cytokines plasma levels in schizophrenia was assessed, including IL-10, only significant trends have been observed for IL-1RA, sIL-2R and IL-6, providing evidence of an inflammatory syndrome in schizophrenia." (PMID 21658228, 2011). "Alternatively, IL-10 expression probably triggers Th2 cell-derived immune responses to infectious pathogens or other environmental stressors in neonates; subsequently these cellular events might play a pivotal role in schizophrenia development." (PMID 23675088, 2008). "The main objective of this study was to assess the effects of ECT on cytokines such as IL-6, IL-12, IL-5, IL-10 and TGF-β1 in patients with treatment-resistant schizophrenia." (PMID 39595201, 2024). "There are no data on the impact of combinations of antipsychotics in TRS patients on other cytokines, e.g., IL-2, IL-4, IL-5, IL-10, IL-12, IL-17, IL-23 and TGF-β1, although their involvement in schizophrenia pathophysiology has been demonstrated." (PMID 39595201, 2024). "The signs of activation of Th2 immune response in schizophrenia include the increase of the IL-4 and IL-10 levels in blood serum, decrease of Th1/Th2 cytokine level ratio (IFN-γ/IL-4, IFN-γ/IL-10, IL-2/IL-4, TNF-α/IL-4)." (PMID 39944368, 2023). "Cytokine levels including IL-2, IL-4, IL-6, IL-10, TNF-α, and IFN-γ were tested, and we found significantly higher levels of IL-6 in patients with schizophrenia (P < 0.01)." (PMID 38066312, 2023).
schizophrenia (continued). "We found higher TGF-α (p = 0.014), IFN-γ (p = 0.036), IL-5 (p < 0.001), IL-6 (p = 0.047), IL-8 (p = 0.005), IL-10 (p < 0.001), IL-15 (p = 0.007), IL-1RA (p = 0.007), and TNF-α (p < 0.001) levels in patients with schizophrenia compared with healthy individuals." (PMID 36556337, 2022). "Specific interleukins (Il-10, IL-10, and TGF-α) are state markers and increase during acute phases of schizophrenia, but are normalized with antipsychotic medication." (PMID 34595576, 2022). "We found higher TGF-α (p = 0.014), IFN-γ (p = 0.036), IL-5 (p < 0.001), IL-6 (p = 0.047), IL-8 (p = 0.005), IL-10 (p <0.001), IL-15 (p = 0.007), IL-1RA (p = 0.007), and TNF-α (p < 0.001) levels in patients with schizophrenia than in healthy individuals." (PMID 36556337, 2022). "The first major finding of this study is that IL-23, IL-6, IL-17, and TNF-α were considerably greater in MNP than in SNP, while IL-1β, IL-22, G-CSF, IL-21, IL-17, IL-10, and TNF-α were significantly higher in schizophrenia than in controls." (PMID 36256663, 2022). "A meta-analysis showed increased levels of IL-6, IL-8, IL-10, IL-12, IL-1β, IFN-γ, TNF-α, and TGF-β in the blood of patients with schizophrenia, which was similar to our findings." (PMID 35223927, 2022). "We also investigated markers of inflammatory response (C-reactive protein, IL-2, IL-6, IL-10), the activity of leukocytic elastase (LE) and α1-proteinase inhibitor (a1-PI), antibodies to S100B and myelin basic protein (MBP) in schizophrenia." (PMID 34025476, 2021). "In a 6-week study, taking SGA (risperidone or olanzapine) during the first episode of schizophrenia (FEP), patients with a normal BMI resulted in a decrease in IL-1RA and IL-10." (PMID 34065135, 2021). "To this end, we focused on a panel of plasma cytokines (IL-1β, IL-6, IL-10, TNF-α, and IFN-γ), which have been used previously to assess signs of peripheral inflammation in major psychiatric disorders such as schizophrenia and animal models of MIA." (PMID 33230204, 2021). "Significantly higher plasma levels of IL-6, IL-10, and TNF-α were, however, detected in schizophrenia patients treated with olanzapine or clozapine, as compared with normal controls." (PMID 33746786, 2021). "We determined the plasma levels of six cytokines (IL-1β, IL-4, IL-6, IL-10, IL-12 and TNF-α) in schizophrenia patients and healthy controls." (PMID 32038109, 2020). "In all patients with schizophrenia, our results showed that plasma levels of SIRT1 were negatively correlated with IL-6 (r = −0.345, P = 0.011), IL-10 (r = −0.276, P = 0.043), and TNF-α (r = −0.393, P = 0.003)." (PMID 33324265, 2020). "In another study of schizophrenia, consumption of Bifidobacterium breve A-1 for 4 weeks improved PANSS and anxiety/depression scores, increased levels of IFN-γ, IL-1R1, IL-10, IL-22, and decreased levels of TNF-α." (PMID 32226399, 2020). "However, our study did not observe a significant association between peripheral IL-10 and clinical assessments in schizophrenia, which might be due to several confounding factors including the relatively small sample size and antipsychotic medication." (PMID 30792621, 2019). "Here, we analyzed changes in serum concentrations of cytokines (IL-1β, IL-2, IL-4, IL-6, IL-10, IL-21, APRIL, BAFF, PBEF/Visfatin, IFN-α, and TNF-α) and growth/neurotrophic factors (GM-CSF, NRG1-β1, NGF-β, and GDNF) in patients with schizophrenia in an exacerbation phase." (PMID 37239308, 2023). "Additionally, our previous research suggested that CRP, IL10, and BDNF, which are regulated by ERVW-1, can be used as serum biomarkers of schizophrenia." (PMID 37376599, 2023). "Therefore, we measured the following pro- and anti- inflammatory macrophage marker mRNAs : CD64, CD206, IL-10, and CD86 (M2b marker) in the dorsolateral prefrontal cortex of people with schizophrenia and unaffected controls." (PMID 35844224, 2022).
schizophrenia (continued). "Also we investigated associations between some immunological patterns and markers of inflammatory response (CRP, IL-2, IL-6, IL-10, the activity of LE and a1-PI, antibodies to S100B and MBP) with clinical symptoms in schizophrenia." (PMID 34025476, 2021). "Furthermore, the ratio of IL-17 and IL-10 expression in NK cells and CD4+ T cells was significantly increased in patients with stable schizophrenia." (PMID 33182582, 2020). "It was also noted that the dysregulation of systemic IL-10 was also related to the negative and general symptoms of schizophrenia, as well as cognitive function, indicating a link between systemic IL-10, WM integrity and clinical symptoms in schizophrenia." (PMID 30792621, 2019). "Interestingly, the activation of ErbB resulted in a higher production of the anti-inflammatory cytokine IL-10 in healthy individuals as compared to TLR-related IL-10 responses, and this ErbB-dependent IL-10 release was much less dominant in schizophrenia." (PMID 28646138, 2017). "Therefore, the reduction in IL-17 and IL-10, following ECT seen in this study, may have a long-term beneficial effect on schizophrenia symptoms." (PMID 40364201, 2025). "Since both the immunological background of drug resistance in patients with schizophrenia and the effects of ECT on cytokines have been insufficiently studied, we decided to examine immunology molecules such as IL-1β, IP-10, IL-17, IL-10, TNF-α, and sIL-2 receptor in TRS patients treated with ECT." (PMID 40364201, 2025). "One meta-analysis showed that acutely relapsed patients with schizophrenia have increased levels of peripheral interleukins (IL) including IL-6, IL-8, tumor necrosis factor alpha (TNF-α), interferon gamma (IFN-γ) but reduced levels of IL-10 when compared with healthy controls." (PMID 33667853, 2021). "However, there were no other significant correlations between SIRT1, IL-6, and IL-10 levels and MetS components in schizophrenia patients (all P > 0.05)." (PMID 33324265, 2020). "Elevated IL-6 levels in childhood might lead to the development of schizophrenia in young adulthood 30, and significant correlations have been found between anti-inflammatory IL-4 and IL-10 with negative symptoms in EOS patients." (PMID 32038109, 2020). "Although it remains unclear why the association between systemic IL-10 and WM integrity only existed in schizophrenia patients but not in controls, we assumed that microstructural WM might be more sensitive to IL-10 in patients than healthy subjects." (PMID 30792621, 2019). "For testing of cohort 9, which comprised help-seeking prodromal individuals (18 who later developed schizophrenia and 58 who did not), the assays for CA, IL10, IL13 and SGOT were excluded for failing QC, resulting in a 22-analyte panel (the same panel tested on cohort 6)." (PMID 26171982, 2015). "Level of IL10 increasing in the cerebrospinal fluid of schizophrenics has been described before; a previous study has mentioned that a strong relationship between an increased IL10 level in cerebrospinal fluid and negative symptoms of schizophrenia was observed." (PMID 23951054, 2013). "Alterations in IFN-γ levels are controversial: several research groups have found no significant alterations of IFN-γ and IL-10 levels, whereas other studies show either increased or decreased levels of IFN-γ in patients with schizophrenia." (PMID 36556337, 2022). "As a result of the study, new information was obtained on the immuno-inflammatory profile and the levels of key regulatory cytokines IL-10 and IL-12p40, as well as neurotrophin NGF in patients with paranoid schizophrenia with severe negative symptoms." (PMID 35265356, 2021). "The study found that IL-10 did not have any effect on cognition if measured alone; however, COMT alone had an impact on language and schizophrenia." (PMID 34725583, 2021).